TLR4 (toll like receptor 4)
Diseases named in the same sentence as TLR4 in open-access papers (continued):
Sharing a sentence is not in itself a finding about the gene and the disease.
cancer (continued). "Ultimately, we demonstrate that the induction of the antimicrobial protein S100A15 in cancer and non-cancer oral mucosa-derived cell lines are mediated by TLR4/2-dependent mechanisms." (PMID 36982421, 2023). "Previous studies have shown that both TLR4 and NLRP3 are upregulated in many human cancers." (PMID 37701157, 2023). "In cancer, a PTX3/TLR4 interaction has been recently reported only for invasive melanoma." (PMID 37749607, 2023). "In colitis-associated cancer (CAC) models, mice with Col6a1+ fibroblast-specific deletion of Stat3 or Ikbkb (but not Tlr4 or Myd88) demonstrate reduced cancer development." (PMID 36591258, 2022). "Recent data indicate that certain murine cancer cells induce muscle wasting by releasing Hsp70 and Hsp90 through extracellular vesicles (EVs) to activate p38β MAPK-mediated catabolic pathways primarily through Toll-like receptor 4 (TLR4)." (PMID 36078164, 2022). "A myriad of research groups have investigated the LPS in Gram-negative bacteria that bind to TLR4 in order to create a cancer vaccine." (PMID 35745800, 2022). "Additionally, LPS upregulates programmed cell death ligand 1 (PD-L1) through the TLR4/MyD88/AKT/NF-κB signaling pathway and induces the depletion and apoptosis of tumor-infiltrating lymphocytes (TILs), thereby promoting cancer immune evasion." (PMID 35309293, 2022). "Although previous studies concluded that S100A4 could interact with the following membrane receptors, including RAGE, EGFR, ERBB2, TLR4, and IL10R, these findings were derived from the nervous system or cancer-related studies." (PMID 36361563, 2022). "At the same time, LPS functions as a major component of the cell wall of Gram-negative bacteria, which can be recognized by TLR-4 and alter the immune response in different cancer patients." (PMID 35672846, 2022). "For cancer-elicited intrinsic inflammation, puerarin was able to regulate macrophage polarization and the expression of proinflammatory cytokines and genes, including TNF-α, IL-12, NF-κB, and TLR4." (PMID 35935578, 2022). "Therefore, in addition to cancer disease, it is likely that S100A8/TLR4/MD-2 axis can be a promising therapeutic target against other inflammation-associated diseases." (PMID 35780158, 2022). "Together, these results identify TLR4 as a cellular BEA sensor and define BEA as a potent activator of BMDCs, implying that this compound can be exploited as a promising candidate structure for vaccine adjuvants or cancer immunotherapies." (PMID 35464417, 2022). "The downstream signaling pathways of TLR4, such as NF-κB, MAPKs and PI3K pathways, can further help cell growth and proliferation, and may also assist in the progression of cancer." (PMID 35955552, 2022). "The Toll-Like Receptor 4 (TLR4)/Nuclear Factor kappa-B (NF-κB)/mitogen-activated protein kinase (MAPK) signaling pathway was also activated in a variety of cancer cells and highly related to the occurrence and development of cancer." (PMID 35859766, 2022). "Here, we have concentrated on the function of TLR4, TLR7, and TLR9 in the cancer in this section." (PMID 35801728, 2022). "Given the importance of the TLR4 pathway in cancer progression, it’s not surprising that currently most of the inhibitors developed are directed against TLR4." (PMID 34884547, 2021). "UBE2D2 and NFKB2 may go through TLR4 to influence IRF1 to destroy the immune system and promote the occurrence and development of cancer." (PMID 34445498, 2021). "B cells liberate IgG and can be cancer-derived, so the M2b phenotype can be induced directly from monocytes and not necessarily has to pass first from a TLR4 activated macrophage and then shift to M2b." (PMID 34177892, 2021). "This is not surprising considering that TLR4 is related to cancer aggressiveness and poor clinical outcome." (PMID 34540671, 2021).
cancer (continued). "TLR4 and TLR9 could also orchestrate a signal that helps cancer cells to bypass the immune responses by increasing the expression of immunosuppressive cytokines and anti‐apoptosis proteins." (PMID 33336901, 2021). "Activation of TLR4 can increase the expression of costimulator molecules on APC cells and improve antigen presentation, resulting in the activation of cytotoxic T lymphocytes and killing of cancer cells." (PMID 33841142, 2021). "Toll-like receptor 4 (TLR4), a component of innate immunity, plays a key role in cancer." (PMID 34771569, 2021). "The actions of opioids can result from their central or peripheral activity, at opioid as well as non-opioid receptors such as Toll-like receptor 4, which is abundantly expressed on immune cells and some cancer cells." (PMID 35004315, 2021). "We further observed that TLR4 mRNA was not altered in RA of our cancer patients, which is consistent to preclinical data that cancer activates TLR4 in muscle but does not alter TLR4 expression." (PMID 34950660, 2021). "One potential mechanism underlying chemoresistance to 5-FU and oxaliplatin is the ability of Fn to target innate immune signaling pathways such as Toll-like receptor 4 (TLR4) and activating Myeloid differentiation primary response 88 (MyD88) in cancer cells to activate autophagy pathway." (PMID 34642332, 2021). "Toll-like receptor 4 (TLR4) is also involved in the initiation of innate and adaptive immune responses, its increased activity in chronic infectious and inflammatory diseases contributing to the pathogenesis of cancer." (PMID 33435564, 2021). "TLR4 belongs to the TLR family and plays an important role in inflammation and cancer." (PMID 33980826, 2021). "As an activator of the cancer-immunity cycle, high mobility group box 1 is released simultaneously with cancer antigens to act on TLR2 and TLR4 of DCs to promote DC maturation and induce antitumor immune responses when cancer cells cause immunogenic cell death." (PMID 34071550, 2021). "Different studies demonstrate positive as well as negative effects of TLR4 stimulation on cancer development or treatment." (PMID 33669782, 2021). "Especially in the design, the 4T1 cancer membrane can improve tumor targeting (about 3.3-fold higher cancer-targeting efficiency than a control liposome) because of homotypic affinity and MPLA can stimulate an immune response by targeting TLR4." (PMID 35083163, 2021). "So far, the best characterized PRR in carcinoma cells are TLR2 and TLR4." (PMID 35048056, 2021). "The activation of TLR4 by lipopolysaccharide (LPS) promoted cancer proliferation but did not influence apoptosis." (PMID 33469538, 2020). "With respect to TLR4 expression in the cervix, data in the literature are controversial, with some groups detecting an increase and others a reduction during HPV infection or cancer development." (PMID 33013878, 2020). "In ovarian cancer, the cancer cell-derived exosomes could trigger inflammatory responses to go against cancer via the TLR2 and TLR4 signaling pathways." (PMID 32565722, 2020). "Overall, the recent clinical trials that involved either TLR4 agonists or NO donors suggest that these therapies, used alone or in combination with TIS, might be beneficial to treat cancer." (PMID 32370259, 2020). "Neutrophils are also recruited through a TLR4/TRIF/type 1 IFN or a Wnt signaling pathway induced by ferroptotic cancer cells, which are important modulators and potential therapeutic targets against cancer progression." (PMID 33102227, 2020). "So, scientists should consider the oncogene role of TLR4 and TLR9 in cancer cells." (PMID 32380783, 2020). "Moreover activation of two distinct signaling pathways by TLR4 and TNF-α secretion makes TLR4 a promising target for cancer immunotherapy." (PMID 32023919, 2020).
cancer (continued). "NE can activate the extracellular transactivation of membrane receptors such as epidermal growth factor receptor (EGFR) and Toll-like receptor 4 (TLR4), inducing mitogen activated protein kinase (MAPK) signaling and downstream effects, thereby directly promoting cancer cell proliferation." (PMID 33042821, 2020). "Therefore, the significant increase of Bax/Bcl‐2, and the significant reduction in p‐AKT/AKT and TLR4/NF‐κB indicated that combined treatment with Abx and DSF/Cu2+ significantly attenuates inflammatory effects and promoted the apoptosis of cancer cells." (PMID 32750218, 2020). "Additionally, we found that AMPKα1KO cancer cells such as AMPKα1KO A549, AMPKα1KO MDA-MB-231, and AMPKα1KO MCF-7 cells showed significantly attenuated TLR4-induced migration and invasion." (PMID 33172060, 2020). "It is important to notify that in these cancer cells a specific band of TLR4 protein was lacking full length." (PMID 32533048, 2020). "Having shown that CRBNKO H1299 and CRBNKO MCF7 cells exhibited increases of autophagy activation induced by TLR4 stimulation, we further examined whether CRBN affected the migration and invasion of cancer cells." (PMID 31620128, 2019). "Increased expression and activity of toll-like receptor 4 (TLR4) in chronic infectious and inflammatory conditions is related with cancer progression: its activation induces an inflammatory signaling that increases the tumorigenic potential of cancer cells promoting their immune evasion." (PMID 31186484, 2019). "Stressed and dying cancer cells release endogenous “danger” signals, such as ATP, S100 and HMGB1, which bind and activate the pattern recognition receptors (PRRs), frequently TLR2 or TLR4, to trigger immune responses." (PMID 30987352, 2019). "Not only do these data explain why anti-cytokine strategies do not effectively intervene in cancer cachexia, but also bring forward the translational implication of TLR4 inhibition in the clinical management of cancer cachexia." (PMID 31480237, 2019). "Although TLR4 expression in skeletal muscle cells is not altered by LLC, a study of cancer patients found that TLR4 expression level in skeletal muscle is significantly correlated with low skeletal muscle index and weight loss." (PMID 31480237, 2019). "Many studies have been aimed at identifying the correlation between chronic inflammation mediated by TLR4 and cancer development and progression, but the role of TEX has not yet been investigated." (PMID 31186484, 2019). "RAGE and TLR4 mediate multiple signaling pathways such as mitogen-activated protein kinase (MAPK), PI3K/Akt, and nuclear factor-kappa B (NF-κB) pathways for inflammation and cancer." (PMID 31620141, 2019). "Furthermore, enhanced expression of TLR4 in CRC cells promotes cell survival, epithelial-mesenchymal transition, and downregulates the expression of the death receptor Fas in cancer cells." (PMID 31157230, 2019). "Then we speculate that HMGB1 may induce the expression of RAC1 and CDC42 followed by binding to TLR4, and activate PI3K/AKT signaling pathway, which plays an important role in cancer cell growth and malignant transformation." (PMID 30962261, 2019). "Although previous reports showed that TLR2 and TLR4 are involved in cell migration and invasion, there has been no data about the ligands of cancer cells for TLR2 and TLR4." (PMID 31034495, 2019). "Apart from the biological relevance of TLR2 and TLR4, TLR3 activation with polyinosinic:polycytidylic acid induced apoptosis of in CRC cells, whereas TLR5 activation suppressed CRC growth and induced necrosis of cancer cells in vivo." (PMID 31157230, 2019). "In AMs the activation of TLR4/NLRP3 inflammasome was found severely decreased, adding to the hypothesis of cancer mediated immunesuppression." (PMID 30365491, 2018). "Moreover, TLR4 is expressed in CRC and promotes cancer cells to escape immune-surveillance by stimulating immunosuppressive agents and resistance to apoptosis." (PMID 29883450, 2018).
cancer (continued). "Here, we also confirm the relationship between TRPV1 and the gram-negative bacterial receptor TLR4 by their concurrent expression on DRG cells of the cancer-induced rat model." (PMID 29637027, 2018). "Taken together, DHA-induced cancer cell apoptosis may be mediated with excess ROS, activation of MAPKs, MKP-1, STAT3-NF-κB, Akt, and mTOR signaling and increased in cAMP/cGMP, TLR-4, and PPAR-α." (PMID 30400136, 2018). "Levels of pro-inflammatory cytokines, IL-6 and IL-8, and anti-apoptotic protein, XIAP were measured by real-time PCR whereas the secreted IL-8 was quantitated by ELISA in TLR4-transient knockdown cancer cells with or without CpdA treatment." (PMID 29486738, 2018). "The browning phenotype induced by cancer cachexia might, therefore, be activated indirectly by p38 MAPK, and the presence of TLR4 appears to be important in this process." (PMID 30575787, 2018). "Furthermore, 5-AZA-CdR induced demethylation of the Toll-like receptor 4 (TLR4) promoter, an important modulator of the immune response in various cancers, and increased H3K4 trimethylation and Sp1 binding to reactivate silenced TLR4." (PMID 28572863, 2017). "S100A4 is secreted by both cancer and stromal cells to participate in both paracrine and autocrine signaling through its putative receptor RAGE, as well as through EGFR- and Toll-like receptor-4 (TLR-4)-mediated pathways." (PMID 27127879, 2016). "A synthetic TLR-4 agonist known as glucopyranosyl lipid A (GLA) has been evaluated clinically as an adjuvant for a seasonal influenza vaccine, and is also being developed as a cancer vaccine adjuvant." (PMID 26344626, 2014). "TLR4 and CXCR7 exhibited mostly cytoplasmic and plasmalemmal staining in carcinoma tissues." (PMID 24363762, 2013). "In contrast to the neutrophils of cancer patients, PMA and fMLP caused an increase in TLR4 but not in TLR2 expression levels on the neutrophils of the control group." (PMID 22528050, 2012). "Harnessing the beneficial effects of TLR4 stimulation while eliminating the negative ones remains the challenge for cancer researchers." (PMID 22110526, 2011). "Therapeutic interventions at the level of TLR4 stimulation is a double-edged sword since different studies demonstrate positive as well as negative effects of TLR4 stimulation on cancer development or treatment." (PMID 22110526, 2011). "Much remains to be studied concerning the function of TLR4 on normal nonimmune tissues in correlation with cancer development." (PMID 22110526, 2011). "In general, TLR4 expression was absent or very weak in the normal mucosae collected from biopsy samples and cancer margin samples." (PMID 20145615, 2010). "Noteworthy were a number of hub genes like TLR4, FAS, HLA-DQB1, HLA-DQA1, F2, HLA-C, IFNAR1, which link complex diseases related to metabolic, immunological, infectious, cardiovascular, neuro-psychiatric disorders and cancer." (PMID 18782426, 2008). "The possible apoptotic pathways for anti-cancer effects of curcumin on cell signal transduction include PI3K, Akt, mTOR, ERK5, AP-1, TGF-β, Wnt, β-catenin, Shh, PAK1, Rac1, STAT3, PPARγ, EBPα, NLRP3 inflammasome, p38MAPK, Nrf2, Notch-1, AMPK, TLR-4, and MyD-88." (PMID 41149437, 2025). "Notably, reduction in TLR4 levels did not significantly affect the intrinsic cancer properties of PLC/PRF/5 or HLE cells, as evidenced by the negligible differences observed in migration, invasion, and colony formation ability." (PMID 40237223, 2025). "Various cancer cells in mice secrete unknown soluble factors under ER stress, upregulating the expression of UPR‐related genes like GRP78, Gadd34, CHOP, and XBP1 in bone marrow‐derived macrophages in a toll‐like receptor 4 (TLR4)‐dependent manner." (PMID 40547943, 2025).
cancer (continued). "When cancer cells die, they release high mobility group box 1 (HMGB1) into the TME, which activates the innate immune system by interacting with several pattern recognition receptors (PRRs), such as Toll-like receptors 2 and 4 (TLR2, TLR4) and the receptor for advanced glycation end products (RAGE)." (PMID 41153383, 2025). "Additionally, LPS is an activator of toll-like receptor 4 (TLR4), and the activation of downstream signaling pathways (including nuclear factors-κB (NF-κB) pathway and MAPK pathway) enhances the invasion and migration of cancer cells." (PMID 40839565, 2025). "Similarly, the interaction with TLR4 and TLR6 could indicate a role in the innate immune response, which is often dysregulated in cancer." (PMID 40343258, 2025). "Such experiments, combined with knockout mice lacking specific immune receptors (e.g., TLR4, IL-6), could clarify which inflammatory pathways are indispensable for microbiota-driven cancer promotion." (PMID 41374093, 2025). "Although we did not assess TLR4 expression directly, prior studies suggest that oral epithelial and carcinoma cells can express functional TLR4 under inflammatory conditions, which may contribute to LPS responsiveness." (PMID 40338411, 2025). "However, chronic treatment resulted in reduced cancer invasiveness among Myd88KO mice while the absence of functional Tlr4 did not influence BC development or progression." (PMID 39000291, 2024). "Unexpectedly, the inhibition of heparanase blocked the whole process, strongly supporting the idea that functional heparanase is crucial for activation of TLR4 and heparan sulfate is not sufficient per se to produce the observed effects on cancer cell stemness." (PMID 39349458, 2024). "The first is TLR agonist, which has been developed to activate TLR3, TLR4, TLR5, TLR7 and TLR9, most of which is still in clinical trials, among which MPLA as a TLR4 agonist and imiquimod as a TLR7 agonist has been approved by FDA for infectious diseases or cancer." (PMID 36650562, 2023). "Ampelopsin exerts its anti-cancer ability through the regulation of growth factor receptor (VEGFR2 and PDGFRβ) and TRAIL/TRAIL-R pathways; moreover, its anti-inflammatory ability is exerted through the modulation of the toll-like receptor 4 (TLR4) pathway or binding to the ryanodine receptor." (PMID 35624699, 2022). "Thus, cell death cannot be sensed as immunogenic in the absence of HMGB1 in cancer cells or TLR4 in myeloid cells." (PMID 36429101, 2022). "Although the most advanced knowledge has been generated around the therapies targeting PD-1/PDL-1 or CTLA-4, there are multiple other important pathways that may impact the immune response to cancer involving many genes, in particular LAG-3, TLR-4, VISTA, TIM-3, TIGIT, ICOS, OX40, and GITR5." (PMID 33911192, 2021). "Further investigation found that trapped cancer cells could internalize NETs via toll like receptor TLR4/9, leading to the activation of inflammatory signalling such as NFκB, MAPK/p38 and STAT3 pathway in cancer cells and thereby facilitates metastatic outgrowth." (PMID 34271947, 2021). "As a common effector of TLR4 and inflammatory cytokine receptors that promote muscle wasting including TNFα, IL-6, IL-1β and members of the TGFβ superfamily including TGFβ and activin A/myostatin, p38β MAPK plays a central role in mediating muscle wasting in murine models of cancer." (PMID 34950660, 2021).